LINC02202 (long independently transcribed non-coding RNA 2202)
Gene: Long non-coding RNA gene on chromosome 5 (159,099,960 to 159,162,049, forward strand). Ensembl gene ENSG00000245812.
Diseases named in the same sentence as LINC02202 in open-access papers:
LINC02202 is named in the same sentence as 2 diseases in open-access papers, as found by Europe PMC text mining. Sharing a sentence is not in itself a finding about the gene and the disease. The quoted sentences say what the papers report.
melanoma (1 paper, 2024). A malignant, usually aggressive tumor composed of atypical, neoplastic melanocytes. "In our study, we found that LINC02202 is highly expressed in melanoma and can regulate the expression of miR‐526b‐3p/XBP1/PD‐L1 axis." (PMID 38520212, 2024). "Through the regulation of the miR‐526b‐3p/XBP1 signalling pathway, LINC02202 may play a role in tumour progression and immune infiltration and inhibiting the expression of LINC02202 can increase the efficacy of immunotherapy for melanoma." (PMID 38520212, 2024).
LINC02202 also shares sentences with these, for which no sentence is quoted: tumour (1 paper).